MTOR (mechanistic target of rapamycin kinase)
Diseases named in the same sentence as MTOR in open-access papers (continued):
Sharing a sentence is not in itself a finding about the gene and the disease.
Renal cyst (39 papers, 2008 to 2025). A fluid filled sac in the kidney. "The activation of AMPK is known to inhibit CFTR-mediated chloride secretion and mTOR-mediated cell proliferation, which are two underlying mechanisms of renal cyst growth." (PMID 33261193, 2020). "Targeting PRAS40 directly or suppressing PRAS40 expression indirectly through enhancement of miR-142-3p impairs the formation of TSC-associated renal cysts, which may provide promising therapeutic approaches for diseases with hyperactivated mTOR signaling." (PMID 39333852, 2024). "Hartman found that Rapamycin enhanced cilia formation in TSC1 and TSC2 null cells and concluded that the efficacy of mTOR inhibitors on renal cystic disease in patients carrying a TSC mutation or PKD1/TSC2-CGS may differ from its efficacy in ADPKD." (PMID 26077033, 2015). "In this study, we discovered the mTOR/miR-142-3p/PRAS40 signaling cascade and evaluated its significance in TSC2 deficiency-induced renal cyst formation." (PMID 39333852, 2024). "In ADPKD, signaling pathways activated in renal cysts by loss of PKD1 include many known to be activated and growth-promoting in cancer including WNT/CTNNB1, PI3K/AKT, mTOR/S6K, RAF/MEK/ERK, SRC, MYC, AURKA, and others." (PMID 37542051, 2023). "Preclinical FLCN-deficient mouse models demonstrated activation of AKT-mTOR pathway, with the mTOR inhibitor rapamycin halting renal cyst and tumor growth in these animals." (PMID 36421797, 2022). "This increase in β-catenin and mTOR signaling, as well as TGF-β1 overexpression, has been linked to renal cyst formation and tissue fibrosis." (PMID 35468900, 2022). "It is possible that this is the natural history of TSC renal cysts or that the increasing use of mTOR inhibitors has decreased the prevalence of renal cysts in the modern era." (PMID 35292049, 2022). "Additional studies are needed to delineate the interactions between CaMK4, GSK3β, and mTOR in the setting of renal cystic disease." (PMID 36002021, 2022). "Among several cancer pathways found to be dysregulated in ADPKD, activation of the mechanistic/mammalian target of rapamycin (mTOR) pathway was found to contribute to renal cyst cell proliferation in patients and ADPKD animal models." (PMID 33238462, 2020). "Metformin, a pharmacological activator of AMPK, inhibits both CFTR and mTOR pathways, and significantly arrests the growth of renal cysts in vitro and in vivo." (PMID 29897930, 2018). "We show here that CaSR activation had a positive effect also on mTOR activity, which is upregulated in cystic kidney epithelial cells showing altered cell proliferation." (PMID 29632324, 2018). "We observed a common increase in Akt and S6 phosphorylation in cystic kidneys compared to controls, indicating increased mTOR activity." (PMID 27356569, 2016). "Similar to renal cysts developed from our Flcnflox/flox/Ksp-Cre mice, these allograft tumors also exhibited the activation of the mTOR pathway, which is consistent with the previous findings in FLCN-deficient cell lines and animal models." (PMID 26418749, 2015). "Human studies show that mTOR activity is upregulated in renal cyst lining epithelial cells in a patient with ADPKD." (PMID 23304619, 2012). "Some experimental studies have suggested a beneficial effect of the mammalian target of rapamycin (mTOR) inhibitor use on hepatic and renal cyst growth in patients with autosomal dominant polycystic kidney disease (ADPKD)." (PMID 23304619, 2012). "mTOR activity is upregulated in renal cyst lining epithelial cells in patient with ADPKD, suggesting a potential benefit of mTOR inhibitor treatment in reducing renal and hepatic cyst growth." (PMID 23304619, 2012). "The activation of the mTOR pathway has been reported to contribute to the pathogenesis of cystic kidney diseases." (PMID 22253885, 2012). "Complete loss of AP-2β in nephron progenitor cells caused an absence of distal convoluted tubules, renal cysts, and fibrosis with β-catenin/mTOR hyperactivation, and early postnatal death." (PMID 35468900, 2022).
Renal cyst (continued). "Moreover, the PI3K/AKT/mTOR pathway was reported to encourage the growth of renal cysts and increase their size and proliferation." (PMID 36422197, 2022). "Loss of such a compensatory mechanism may also explain why deletion of FNIP1 synergized with TSC1 deletion to activate mTOR and subsequently resulted in accelerated renal cyst formation in mice." (PMID 35883484, 2022). "In this study, we utilized mice with constitutive deletion of the Fnip1 gene to show that the loss of Fnip1 is sufficient to result in renal cyst formation, which was characterized by decreased AMPK activation, increased mTOR activation, and metabolic hyperactivation." (PMID 29897930, 2018). "In addition, the epithelium of both ADPKD cystic kidneys and Pkd1 mutant kidneys displayed enhanced mTORC1 activity, as evidenced by immunohistochemical analysis of S6K and mTOR phosphorylation levels." (PMID 19863783, 2009). "Previous studies of cystic kidneys implicated several pathways thought to contribute to the pathogenesis of renal cysts' formation like mTOR signalling, MAPK (Mitogen-Activated Protein Kinase) signalling, Wnt signalling, and the TGF-β (Transforming Growth Factor-β) pathway." (PMID 19102782, 2008). "The molecular events between activated mTOR and renal cysts/AMLs are still largely unknown." (PMID 39333852, 2024). "Thus, a better understanding of the pathways that contribute to mTOR activation in renal cystic disease may be important for the development of new therapies." (PMID 36002021, 2022). "According to the study, RNA‐seq analysis on cystic kidneys of ADPKD mutant mice detected dysregulated lncRNAs and confirmed that Hoxb3os lncRNA alters mTOR signaling and mitochondrial respiration and functions as a negative regulator." (PMID 38958113, 2024). "In renal cyst (RC) cells, the mTOR cascade acts as the downstream of CXCL12/CXCR4 axis, and CXCR4-mediated CXCL2 recognition can selectively active the mTOR signaling to enhance RC cells proliferation." (PMID 32483450, 2020). "Tsc1 haploinsufficiency without mTOR activation was shown to lead to renal cyst formation in TSC1+/− mice." (PMID 35883484, 2022). "All these clues implied that BHD gene may play an important role in suppression of cystogenesis and tumorigenesis and that its inactivation could lead to the formation of renal cysts and RCC through the mTOR pathway." (PMID 18974783, 2008).
pneumonitis (38 papers, 2011 to 2025). An inflammatory process affecting the lung parenchyma. "MTOR inhibitor treatment-induced pneumonitis, similarly to the case of immunotherapy, is associated with treatment outcomes." (PMID 36213163, 2022). "mTOR inhibitor-associated pneumonitis most commonly presents as either cryptogenic organizing pneumonia (COP) or nonspecific interstitial pneumonia (NSIP)." (PMID 33801385, 2021). "Generally, in mTOR inhibitor pneumonitis, pulmonary function tests are associated with a restrictive pattern or an isolated reduction in diffusing capacity." (PMID 33801385, 2021). "The benefit of mTOR inhibitors should be evaluated on a case-by-case basis given the risk for pneumonitis." (PMID 33330049, 2020). "Immunotherapeutic and molecular targeted antineoplastic agents including checkpoint inhibitors, idelalisib, mTOR inhibitors, and, to a lesser extent, ibrutinib have been associated with drug-related pneumonitis." (PMID 30700842, 2019). "Appropriate management strategies for preventing and treating recognized AEs associated with mTOR inhibitors as a class in both oncology and immunosuppressive settings (e.g., stomatitis, rash, pneumonitis) have been well described previously." (PMID 29774169, 2018). "Given that gedatolisib inhibits both PI3 K and mTOR, the side effect profile and risk of pneumonitis may be less favorable." (PMID 40471518, 2025). "Indeed, patients treated with MTOR inhibitors have higher susceptibility to pneumonitis and tissue edema." (PMID 39510184, 2024). "Those include but are not limited to drug-induced pneumonitis associated with mTOR inhibitors, immune checkpoint inhibitor therapy-related pneumonitis, severe viral pneumonia, radiation pneumonitis, and eosinophilic pneumonia associated with chimeric antigen receptor T cell (CAR T) therapy." (PMID 36354934, 2022). "The underlying pathogenesis of mTOR-induced pneumonitis is unknown and it is generally considered reversible and dose-dependent." (PMID 29518028, 2018). "The adverse effects of mTOR inhibitors, such as everolimus and sirolimus, include stomatitis, increased risk of infection, immunosuppression, abnormalities in renal function, fatigue, and pneumonitis." (PMID 27181099, 2016). "This is a well-known side effect of mTOR inhibitors such as everolimus, with pneumonitis seen in both the BOLERO-2 trial (3%) and PrE0102 trial (17% overall, 6% grade 3)." (PMID 40471518, 2025). "Although numerous PI3K/AKT/mTOR pathway inhibitors have been extensively studied, their potential adverse effects, such as severe hepatotoxicity and pneumonitis, have largely restricted the clinical application of these inhibitors." (PMID 38365306, 2024). "Pneumonitis is a dose dependent adverse event, the severity of pneumonitis regress with dose reduction, and usually ends after discontinuation of mTOR inhibition." (PMID 36213163, 2022). "Everolimus-induced pneumonitis is a class effect AE, also seen with other mTOR inhibitors such as temsirolimus and sirolimus." (PMID 35641203, 2022). "Studies conducted in patients with metastatic cancers (renal, breast or lung) reported mTOR inhibitor-related pneumonitis with a large variation in incidence." (PMID 30700842, 2019). "Patients with mTOR pneumonitis can be asymptomatic or have only mild symptoms, thus careful monitoring is required and treatment with mTOR inhibitors can often be continued." (PMID 24281308, 2012). "Pneumonitis is a known serious toxicity of mTOR inhibitors so study staff was vigilant regarding stopping study drug promptly if respiratory symptoms were reported." (PMID 21915260, 2011). "The reported incidence of mTOR inhibitor-induced pneumonitis varies by population." (PMID 41322782, 2025). "Drug-induced pneumonitis is a recognized yet often underdiagnosed complication of mammalian target of rapamycin (mTOR) inhibitors - immunosuppressive agents such as everolimus that block cellular proliferation pathways - particularly among solid organ transplant recipients." (PMID 41322782, 2025).
pneumonitis (continued). "Some rare and severe adverse events with mTOR inhibitors have been reported, which could result in discontinuation of treatment and fatal outcome, for example, infection and pneumonitis." (PMID 39224564, 2024). "The syndrome of “rapamycin lung” is a diffuse pneumonitis observed with mTOR (mammalian target of rapamycin) inhibitors (e.g., everolimus, sirolimus and temsirolimus), generally in concert with other infections, including community-acquired respiratory viruses and Pneumocystis." (PMID 36354934, 2022). "Taken the role of mTOR pathway in the regulation of the innate and adaptive immune systems into consideration, immune mediated processes probably plays a role in the development of pneumonitis, similarly to the immune checkpoint inhibitors." (PMID 36213163, 2022). "This patient's treatment course was complicated by mTOR-induced pneumonitis." (PMID 30863722, 2019). "Furthermore, since the idelalisib-induced pneumonitis is consistent with mTOR inhibitor-induced pneumonitis, this biological side-effect appears to be a rare but severe class effect." (PMID 31443495, 2019). "Although several studies now show improved pulmonary function with sirolimus treatment, it is not clear that that long term benefits will outweigh risks, especially considering that sirolimus is an immunosuppressant and pneumonitis is a known and potentially serious toxicity of mTOR inhibitors." (PMID 21915260, 2011). "Notably, pneumonitis is a serious side effect of mTOR inhibitors." (PMID 35040598, 2022). "The exact mechanism of development of mTOR inhibitor-related pneumonitis remains unknown." (PMID 35641203, 2022). "One possible explanation for this finding was that the use of mTOR inhibitors could cause non-infectious pneumonitis, although the mechanisms of mTOR related pneumonitis was still unknown." (PMID 23785409, 2013). "Drug-related pneumonitis can also occur with chemotherapy (docetaxel, gemcitabine, bleomycin), targeted therapy (e.g. EGFR inhibitors, mTOR inhibitors), and radiation therapy." (PMID 30176946, 2018). "Our data suggest that the AKT/mTOR and SMO-Hh pathway probably contribute to radiotherapy-induced esophagitis, while the AKT pathway probably contributes to the pneumonitis." (PMID 26991123, 2016). "The mTOR inhibitor everolimus demonstrates efficacy in SSA-refractory pulmonary or gastroenteropancreatic NENs with median PFS of 16.4 months versus 11.3 months for placebo, though requires monitoring for pneumonitis (13% incidence)." (PMID 41333794, 2025). "There is some clinical concern with the use of mTOR or dual mTOR/PI3K inhibitors as non-infectious pneumonitis is a well-recognized serious adverse event that can occur." (PMID 29518028, 2018).
hemimegalencephaly (37 papers, 2013 to 2025). "The spectrum of brain malformations associated with mTOR pathway dysregulation ranges from small FCDs to hemimegalencephaly (HME)." (PMID 39062615, 2024). "Recently, defects in the protein kinase mTOR (mammalian target of rapamycin) and its associated pathway have been correlated with hemimegalencephaly (HME)." (PMID 32140648, 2020). "Using exome sequencing, recent studies have identified de novo germline and somatic mutations of PI3K-AKT-mTOR components (PIK3CA, AKT3, and MTOR genes) in patients with hemimegalencephaly." (PMID 26541977, 2015). "While somatic MTOR mutations have been recognized in tumors for many years, and more recently in hemimegalencephaly, germline MTOR mutations have rarely been described." (PMID 26542245, 2015). "In FCD type 2 and hemimegalencephaly linked to mosaic variants in genes of the mTOR pathway, a similar correlation between the size of the lesion or the epileptogenic activity and the mosaic rate has also been reported confirming the pro-epileptogenic role of mutated cells." (PMID 33407896, 2021). "In addition, an mTOR somatic mutation at C4448T that causes C1483Y substitution was observed in hemimegalencephaly brain." (PMID 24795562, 2014). "Recently, somatic mutations of Akt, PI3K, and mTOR were reported in the hemimegalencephaly brain." (PMID 24795562, 2014). "MTOR is the most frequent causative gene for FCD IIa or IIb and the second common causative gene for hemimegalencephaly." (PMID 35040598, 2022). "Numerous studies show that mutations in different genes acting as regulators of mTOR signalling and, consequently, the activation of the mTOR pathway lead to megalencephaly or hemimegalencephaly." (PMID 34576223, 2021). "Noteworthy, enhanced mTOR signaling was also identified in hemimegalencephaly, and in enlarged dysmorphic neurons and balloon cells of Taylor-type FCD and cortical tubers." (PMID 24062718, 2013). "Therefore, our observations of mTOR cascade activation in FCD are consistent with previous reports that indicate enhanced mTOR activation in hemimegalencephaly and ganglioglioma pathologies and distinguish tubers from FCD." (PMID 40195216, 2025). "Therefore, our observations of mTOR cascade activation in FCD are consistent with previous reports that indicate enhanced mTOR activation in hemimegalencephaly and ganglioglioma pathologies and distinguishes tubers from FCD." (PMID 39483922, 2024). "Hemimegalencephaly is part of a spectrum of disorders, increasingly referred to as mTORopathies, which arise as a result of dysregulation or hyperactivation of the mammalian target of rapamycin (mTOR)-signaling cascade resulting in less restricted cell growth and survival." (PMID 36120272, 2022). "Since PTEN is a constitutive inhibitor of mTOR, its loss of function causes the hyperactivation of mTOR and somatic mutations of PTEN cause a variety of cortical malformations depending in severity on the extent of the mutation, ranging from hemimegalencephaly to T2FCD43,65,66." (PMID 33273479, 2020). "Similar and related disorders are caused by somatic mutations in the genes of the PI3K/AKT/mTOR (mammalian target of rapamycin) pathway, which include PTEN, PIK3R2 (MCAP), AKT1 (Proteus syndrome), AKT2 (asymmetric overgrowth and hypoglycemia), and AKT3 (hemimegalencephaly)." (PMID 28525374, 2017). "Although megalencephaly and hemimegalencephaly are not typical symptoms of TSC, the case reports confirm the involvement of the activation of the mTOR pathway in processes leading to brain overgrowth, similar to our studies with Tsc2+/− mice." (PMID 34576223, 2021).
Intellectual disability (37 papers, 2012 to 2025). "Here, the authors identify de novo mutations in RHEB, an mTOR activator protein, in patients with intellectual disability associated with megalencephaly and find a role for RHEB in regulating neuronal soma size and migration in vitro and in vivo." (PMID 29051493, 2017). "De novo mutations in specific mTOR pathway genes cause brain overgrowth in the context of intellectual disability (ID)." (PMID 29051493, 2017). "The alteration of the insulin signaling/mTOR (mammalian target of rapamycin) pathways represents an early event in the DS brain and likely contributes to cerebral dysfunctions and intellectual disability." (PMID 39756004, 2025). "In both patients and rodent models, mutations to the phosphatase and tensin homolog gene (PTEN) on chromosome 10 results in hyperactivation of the mTOR pathway, as well as seizures, intellectual disabilities and autistic behaviors." (PMID 37376966, 2023). "The mTOR pathway is dysregulated in several human diseases, including cancer and diabetes as well as intellectual disabilities, such as FXS, Rett syndrome and ASD30." (PMID 30705255, 2019). "In this monogenic disease, the constitutively activated mTOR signaling leads to the formation of benign tumors and additional phenotypic traits such as seizures, intellectual disability and developmental delay." (PMID 27680012, 2016). "Dysregulated protein synthesis has emerged as a prominent process implicated in several monogenic forms of ASD and intellectual disability, as well as in sporadic ASD, and is often accompanied by changes in key signaling pathways upstream of translation such as mTOR." (PMID 37293130, 2023). "Proteins measured include multiple components of the MAPK, MTOR and apoptosis pathways, immediate early gene proteins, and several subunits of ionotropic glutamate receptors, in addition to other proteins known to function in synaptic plasticity and intellectual disability." (PMID 34680922, 2021). "The common signaling cascade reactions of IR/IGF1R include PI3K/AKT/mTOR and RAS/ERK, and the activation of these pathways plays a role in neurodevelopmental disorders such as intellectual disability (ID) and ASD." (PMID 39027477, 2024). "In this context, dysregulation of the mTOR signaling pathway may lead to substantial abnormalities in brain development, contributing to a wide array of neurological disorders, including ASD, seizure, learning impairments, and intellectual disabilities." (PMID 39812094, 2025). "Even though many forms of intellectual disability are thought to be due to changes in synaptic transmission, our results thus show that changes in mTOR or Ras signaling do not result in ubiquitous in vivo changes in synaptic transmission." (PMID 26190969, 2015). "Our data propose that an increase in both MAPK and mTOR pathways possibly leads to aberrant protein synthesis in subjects with ASD, indicating that alteration of mTOR and the MAPK pathways may contribute to intellectual disabilities and to both syndromic and non-syndromic ASD." (PMID 30705255, 2019).